WNT5A (Wnt family member 5A)
Diseases named in the same sentence as WNT5A in open-access papers (continued):
Sharing a sentence is not in itself a finding about the gene and the disease.
cancer (continued). "Emerging data support a contribution of specific Wnt5a downstream signaling pathways to cancer development and progression." (PMID 27571105, 2016). "Wnt5a is the characteristically highly expressed Wnt in cancers with squamous histology and increased Wnt5a levels are also a trademark of lung SCC." (PMID 27876017, 2016). "Many studies have revealed a strong correlation between Wnt5a protein expression level and cancer metastasis." (PMID 27571105, 2016). "Recent studies show the involvement of Wnt5a in regulating cancer cell invasion, metastasis, metabolism and inflammation." (PMID 27571105, 2016). "Here, we will discuss recent findings regarding the molecular mechanisms and the emerging roles of Wnt5a signaling in various cancer types." (PMID 27571105, 2016). "Macrophage recruitment is a character of inflammation and cancer, therefore macrophage-derived Wnt5a is supposed to be a player in these conditions." (PMID 27608847, 2016). "WNT5A is misregulated in a wide range of cancer types, displaying both increased and decreased expression." (PMID 26978652, 2016). "Interesting recent findings of a role for Wnt5a in regulation of cancer cell metabolism also merits further investigation." (PMID 27571105, 2016). "Overall, these data suggest that Wnt5a regulation of cancer cell proliferation is dependent on the context of downstream effectors." (PMID 27571105, 2016). "Does TAM-derived Wnt5a promote cancer cell migration by inducing angiogenesis and lymphangiogenesis?" (PMID 27608847, 2016). "Another study showed that the Wnt5a promotor is hypo-methylated in two multidrug-resistant cancer cell lines MES-SA/Dx5 and MCF7/ADR2 cells." (PMID 27571105, 2016). "A compelling body of studies has revealed that Wnt5a is a regulator in the proliferation of normal and many cancer cell types." (PMID 27895670, 2016). "Wnt5A plays essential roles in developmental and physiological processes, including inflammation, but it also plays a role in cancer." (PMID 28536612, 2016). "Wnt5a activated through Ror2 regulates the expression of matrix metalloproteases (MMPs) which are the most common target genes related to cancer invasion." (PMID 26608372, 2016). "WNT5a has also been reported to be up-regulated in different types of cancer, especially in human PDAC and represents a key cascade molecule in Extracellular Matrix remodeling." (PMID 26958939, 2016). "In PDAC, WNT5a is recurrently over-expressed and exerts a pro-oncogenic function, by promoting proliferation, migration and invasion of cancer cells." (PMID 26958939, 2016). "WNT-5A, owing to its properties of both activating and inhibiting WNT/β-catenin signaling and regulating cell movements, can be linked with cancer pathobiology." (PMID 26514730, 2016). "In non-small-cell lung cancer (NSCLC), overexpression of Wnt5a produced more aggressive cancer, especially in squamous cell carcinomas wherein it was significantly correlated with the Ki-67 proliferation index." (PMID 27571105, 2016). "We here summarize the role of WNT-5A in human pathologies such as fibrosis, inflammation, and cancer." (PMID 26514730, 2016). "In several cancers, Wnt5a was found to promote cell migration, thereby enhancing cancer cell invasion." (PMID 27571105, 2016). "These two reports highlight a new role for Wnt5a signaling as a regulator of cancer cell metabolism." (PMID 27571105, 2016). "With respect to Wnt5a signaling, it has been demonstrated to promote cancer cell migration and invasion, epithelial-mesenchymal transition (EMT), and metastasis, as well as enhance the stemness of cancer stem cells (CSCs) and chemoresistances." (PMID 27895670, 2016). "Wnt5a's role in human cancer is controversial; it can function both as cancer negative regulator and oncogenic factor in a context-dependent manner." (PMID 26967567, 2016).
cancer (continued). "Taken together with the observations that knockdown of Wnt5a reduces the invasion activity of these cancer cells to the half level, these results suggest that the signaling pathway(s) activated by molecules other than Wnt5a are involved in these cell invasion." (PMID 25622531, 2015). "Wnt5a activated Src family kinases (SFKs) and Wnt5a-dependent cancer cell proliferation was dependent on SFKs, yet blockade of receptor-mediated endocytosis did not affect cancer cell proliferation and SFK activity." (PMID 25622531, 2015). "Because Daple serves as a bona fide enhancer of the non-canonical Wnt pathway, we conclude that upregulation or downregulation in Daple expression contributes, at least in part, to the bimodal deregulation of the Wnt5a signaling pathway observed in cancers." (PMID 26126266, 2015). "Many previous studies have demonstrated that Wnt5a is upregulated in various cancers, including pancreatic, gastric and prostate cancers." (PMID 26305508, 2015). "Taken together, these results suggest that Wnt5a-dependent cancer cell proliferation is regulated by a receptor-mediated endocytosis-independent mechanism." (PMID 25622531, 2015). "Taken together, these results indicate that Wnt5a promotes proliferation of certain types of cancer cells in which endogenous Wnt5a is highly expressed." (PMID 25622531, 2015). "Many studies have attempted to determine the prognostic values of ROR2 and Wnt5a in various cancers." (PMID 26305508, 2015). "In this study, we generated a neutralizing anti-Wnt5a monoclonal antibody (mAb5A16) to investigate the mechanism by which Wnt5a regulates cancer cell proliferation." (PMID 25622531, 2015). "Wnt5a is one of the important members in the large family, and it is correlated with various cancers." (PMID 26305508, 2015). "Accumulating evidence indicates that Wnt5a exhibits paradoxical effects in various types of cancer metastasis." (PMID 24944588, 2014). "The aim of the present study was to summarize the previous findings on the roles of Wnt5a and the potential mechanisms in various types of cancer metastasis." (PMID 24944588, 2014). "In this study, Wnt5A was found to be significantly upregulated in MES-SA/Dx5 and MCF7/ADR2 cells, suggesting an important role for the Wnt5A signaling pathway in cancer drug resistance." (PMID 25401518, 2014). "On the one hand, Wnt5a was found frequently upregulated in various cancers, including breast cancer, pancreatic cancer, prostate cancer, and gastric cancer." (PMID 24999479, 2014). "Although the results discussed appear conflicting, it is conceivable that the roles of Wnt5a in cancer metastasis." (PMID 24944588, 2014). "Cell viability of the drug-resistant cancer cells was also reduced by doxorubicin treatment and Wnt5A shRNA transfection, or by Wnt5A depletion." (PMID 25401518, 2014). "Wnt5a mRNA level in cancer tissues was significantly higher than that in adjacent non-malignant tissues." (PMID 24993819, 2014). "As one of the important members in the large Wnt family, Wnt5a has been shown to have close correlation with various cancers." (PMID 24999479, 2014). "As Wnt5A is a secreted protein that affects cells in an autocrine or paracrine manner, activation of Wnt5A/PKA/β-catenin pathway was further confirmed in drug-resistant cancer cells by depleting Wnt5A using a neutralizing anti-Wnt5A antibody." (PMID 25401518, 2014). "Our observations indicate that the distinct functions of WNT5A in cancer are not only due to differences in cellular context (e.g. expression of receptors and other signal transducers)." (PMID 24260410, 2013). "Altogether, our study provides evidence that the distinct activities of WNT5A in cancer can be attributed to the production of two WNT5A isoforms." (PMID 24260410, 2013). "Many studies have documented a crucial role for Wnt5a in cancer progression and metastasis, contributing to cancer cell migration and invasion." (PMID 24156409, 2013).
cancer (continued). "Collectively, these findings underscore the complex functional and prognostic roles of Wnt-5a in cancer." (PMID 23990917, 2013). "As WNT5A inactivation is frequent in hematological malignancies, we also analyzed the expression status of its isoforms in these cancers and corresponding normal tissue." (PMID 24260410, 2013). "In good agreement with these findings, Wnt-5a has been recognized both as a marker of favorable and of poor outcome in primary cancers." (PMID 23990917, 2013). "Wnt5a mRNA expression differed widely in the three urothelial cell lines, with high levels in one carcinoma cell line and low levels in the other cell line in comparison to the normal urothelial cell line." (PMID 23947922, 2013). "The positive expression rate of Wnt5a was 96.7% (29/30), 85.5% (70/83), and 42.9% (10/21) in well-, moderately-, and poorly-differentiated carcinomas, respectively." (PMID 24156409, 2013). "In well-differentiated carcinomas, strong immunostaining for Wnt5a was detected at the glandular luminal border, whereas in poorly differentiated carcinomas the immunoreactivity was markedly reduced." (PMID 24156409, 2013). "With regard to the whole patient cohort, univariate analyses revealed that all these parameters predict BCR-free survival, whereas in low-grade cancers high-Wnt5a expression also predicts favorable outcome." (PMID 23342259, 2012). "High-Wnt5a protein expression was observed in nearly 41% of the cancer cases compared to 82% which we observed in our previous study." (PMID 23342259, 2012). "Wnt5a has ample opportunity to influence cancer cell signaling, resulting in functional promiscuity on cancer development." (PMID 22655072, 2012). "Most studies on Wnt5a expression in cancer patient materials focus on tumorigenesis of primary tumors." (PMID 22655072, 2012). "One crucial aspect of Wnt5a action on cancer cell motility is the presence of concentration gradients." (PMID 22384081, 2012). "Functional studies will be required to determine if Fzd2 mediates Wnt5a-driven invasiveness in these cancer types." (PMID 22384081, 2012). "The first phenotype was characterized by prevalent expression of cancer testis antigens, WNT5A and a Th17 immune phenotype; those characteristics have all been ascribed to a more aggressive behavior of cancer (Class A)." (PMID 22537248, 2012). "Most of the patients (220/365, 60%) with strong Wnt5a immunostaining in cancer tissues also exhibited intense AR staining." (PMID 22039506, 2011). "In nearly 80% of the patients we found strong Wnt5a staining intensity (arbitrary unit 2 or 3) in cancer cores, whereas only 35% patients displayed strong staining in benign tissue samples." (PMID 22039506, 2011). "The difference between Wnt5a staining intensities in cancer and benign samples was found to be significant (p<0.0001) when paired Wilcoxon rank sum test was performed." (PMID 22039506, 2011). "Immunohistochemical analysis of a tissue microarray containing prostate specimens of 503 patients with localized prostate cancer showed significantly higher Wnt5a protein expression in cancer compared to benign cores from the same patients (p<0.0001)." (PMID 22039506, 2011). "Wnt5a is emerging as an important functional and prognostic contributor in several cancers and is commonly silenced by promoter hypermethylation." (PMID 21587258, 2011). "Wnt5a protein expression as illustrated by IHC was significantly higher in cancer areas compared to benign areas." (PMID 22039506, 2011). "Wnt5a protein expression was detected in the cytoplasmic compartment of epithelial cells and occasionally in stromal cells of both cancer and benign tissue specimens." (PMID 22039506, 2011). "Spearman's correlation coefficients (ρ) when Wnt5a protein expression was analyzed for possible correlation with other tissue biomarkers in the cancer cores from 464 PCa patients." (PMID 22039506, 2011).
cancer (continued). "We demonstrate that (i) Wnt5A protein expression is increased in malignant compared to benign human prostate tissue and in cancer cell lines compared to normal." (PMID 20454608, 2010). "We suggest that activation of CaMKII via Wnt5A signaling is advantageous to cancer cell mobility as it suppresses formation of fine filopodia that induce retrograde movement thus reducing cell mobility." (PMID 20454608, 2010). "Expression of Wnt5A protein was also higher in 1542-CP3TX cancer cells compared to matched normal 1542-NPTX cells." (PMID 20454608, 2010). "CamKII and PKC activation by Wnt-5a is maintained in higher organisms and is essential for invasion of cancer cells." (PMID 19603030, 2009). "Studies with much larger sample sets will provide the necessary statistical power to validate the extent of the downregulation of Wnt-5a in cancer." (PMID 19603030, 2009). "As Wnt-5a can counteract the effects of canonical Wnt signalling, it seems clear that its downregulation would be advantageous to cancers driven by canonical Wnt signalling." (PMID 19603030, 2009). "Once an in-depth understanding of the processes by which Wnt-5a brings about its cellular effects is achieved, it is likely that its role in cancer will be clarified." (PMID 19603030, 2009). "Wnt-5a partakes in many of the Wnt-dependent signalling processes used during development, tissue homoeostasis and cancer progression, but its role in the latter is still unclear." (PMID 19603030, 2009). "In this review, we discuss the opposing roles of Wnt-5a in cancer development and show that an account of the Wnt-5a cellular and signalling context should be taken before a functional classification can be made." (PMID 19603030, 2009). "The role of Wnt-5a in cancer and normal tissue is intriguing and the current intense level of research will further our understanding and identify novel targets for therapeutic intervention along with predictive biomarkers for targeted therapy regimes." (PMID 19603030, 2009). "In terms of cancer development, Wnt-5a has, until recently, lived in the shadow of its better-characterised relatives." (PMID 19603030, 2009). "Further study found that BBR could reduce the expression of HNF4α, WNT5A, and cytoplasmic β-catenin in cancer tissues, and the regulation of HNF4α-Wnt5a is a crosstalk between AMPK metabolic pathway and WNT signaling pathway." (PMID 40092702, 2025). "In addition, CAF-derived WNT5A drives the maintenance and expansion of cancer stem cells, and inhibition of WNT5A reduces stemness and chemoresistance." (PMID 41470247, 2025). "Besides IL-6, cancer cell–secreted Wnt5a induces IDO1 expression through β-catenin (CTNNB1) activation in DCs." (PMID 40789452, 2025). "In breast cancer, for example, cancer-associated fibroblasts (CAFs) are major producers of non-canonical Wnt ligands like Wnt5a." (PMID 40376615, 2025). "In addition, cancer-related fibroblasts maintain OC stem cell growth by activating the Wnt5a signaling pathway." (PMID 40567611, 2025). "While secreted WNT5A appears to promote a more aggressive cancer phenotype, WNT5A in extracellular vesicles may exhibit context-dependent effects, potentially inhibiting or promoting cancer progression." (PMID 40223089, 2025). "We demonstrated positive correlation between RUNX3 and WNT5A expression in resected cancer tissue." (PMID 38240752, 2024). "Hence, our study's critical aspect is emphasizing the role of WNT5A in immune cell infiltration and immune escape in different cancers." (PMID 39176352, 2024). "We demonstrate that CAFs signal to proximal OC cells via Wnt5a, inducing a non-canonical Wnt signaling pathway in the cancer cells, causing self-renewal of OCSCs and dedifferentiation of some non-OCSCs into OCSCs." (PMID 38191909, 2024). "In contrast, the WNT5A+ inflammatory fibroblast interacts with cancer cells via IL24:IL20RA and WNT5A:FZD5 pathways, which could promote cancer progression and chemoresistance." (PMID 38744958, 2024).
cancer (continued). "Furthermore, The involvement of Wnt5a in regulation of cancer cell invasion, metastasis, metabolism and inflammation renders it a subject of intense research in oncology." (PMID 38898476, 2024). "Inhibiting cancer cell migration and metastasis requires Wnt-5a signaling." (PMID 39518123, 2024). "This can produce inconsistent conclusions about the role of WNT5A in various cancer types." (PMID 39176352, 2024). "The present study is the initial pan-cancer examination of WNT5A." (PMID 39176352, 2024). "Likewise, a study by Thiele and colleagues (2015) also found that WNT5A overexpression decreased cell proliferation and migration, and increased cancer cell apoptosis." (PMID 39164966, 2024). "The Wnt5a mimicking peptide and agonist Foxy-5 limits cancer cell motility and invasion." (PMID 39518123, 2024). "MSCs are not the only non-malignant cells affected by cancer cells to promote tumor progression since macrophages can acquire a cancer cell migration-stimulating phenotype when exposed to microvesicles (MV) from patients with different cancer types, wherein Wnt5a expression occurs." (PMID 37804416, 2024). "Wnt5a and Wnt8b have been shown to promote cancer progression." (PMID 36814555, 2023). "The ROR1 ligand, Wnt5a, is a cytokine highly expressed in cancer tissues." (PMID 36873868, 2023). "In vitro migration assays showed that a Wnt5a gradient may increase cell motility towards adjacent tissue although homogeneous concentration of Wnt5a inhibits chemotactic migration, thus regulating cancer progression." (PMID 36675086, 2023). "Wnt5a fosters neuronal survival by negatively regulating the cell-cycle, protects against neurodegeneration through glucose metabolism promotion, and displays a high abundance that correlates with cancer aggressiveness." (PMID 35622188, 2023). "To further explore the findings that WNT5A signaling might affect cancer cell behavior, we next examined the effect of WNT5A signaling on the colony formation ability of HCT-116 cells." (PMID 37998393, 2023). "Overexpression of WNT5a could inhibit the progression of EGFR mutant NSCLC by blocking the canonical WNT pathway, indicating that WNT5a plays an anti-cancer role in the development of such NSCLC." (PMID 37486552, 2023). "Wnt5a signaling induces cancer cell migration via Akt phosphorylation." (PMID 35085258, 2022). "The canonical WNT signaling pathway is associated with cell migration, and the WNT5A non-canonical signaling pathway was also found to be associated with a variety of human cancers." (PMID 36385012, 2022). "Also, Wnt5a signaling is reported to modulate the interaction between cancer cells and accessory cells in the microenvironment, contributing to disease progression in solid tumors." (PMID 35210425, 2022). "Studies suggest that Wnt5a's role in tumors may be related to pathways for downstream action, where activation of CamKII induces anti-cancer effects." (PMID 35517407, 2022). "Furthermore, up-regulated expression of Ror1 can be mediated by STAT3 in various types of cancer cells, thereby promoting proliferation of cancer cells in Wnt5a-dependent or -independent manners." (PMID 35493090, 2022). "Our previous findings suggested that high expression of WNT5A in primary PCa tissue is associated with longer overall survival (OS), but not cancer‐specific survival (CSS)." (PMID 33639039, 2021). "It will be interesting to determine whether YAP/TEAD binding to the WNT5A regulatory region is a feature of cancer cell lines or if this merely represents a need for additional studies in other cell types." (PMID 33643710, 2021). "However, most reports studying Wnt5a in GC were carried out before the release, or recent update, of cancer gene and protein expression and analysis databases, such as cBioPortal, TIMER, GEPIA, and The Cancer Proteome Atlas (TCPA)." (PMID 33869179, 2021). "TGF-β, Wnt5a/b, and Notch are important for maintaining cancer stem-like properties." (PMID 34198967, 2021).